PRNP (prion protein (Kanno blood group))
Diseases named in the same sentence as PRNP in open-access papers (continued):
Sharing a sentence is not in itself a finding about the gene and the disease.
scrapie (continued). "Prion diseases in sheep and goats are called scrapie and belong to a group of transmissible spongiform encephalopathies (TSEs) caused by the abnormal misfolding of the prion protein encoded by the prion protein gene (PRNP)." (PMID 31649311, 2019). "Moreover, in small ruminants, such as sheep and goats, a number of polymorphisms associated with scrapie have been reported in the open reading frame (ORF) of the PRNP gene." (PMID 30359416, 2018). "Our challenge data further strengthen the view that the caprine K222 allele is an attractive PRNP variant for TSE resistance breeding since it is not only strongly limiting the transmission of classical scrapie, but as is exemplified here it also has a protective effect against BSE infection." (PMID 28927447, 2017). "Also in goats, field and experimental studies evidenced associations between certain polymorphisms of the PRNP gene and susceptibility/resistance to classical scrapie." (PMID 28691895, 2017). "Scrapie eradication programmes are largely based on the observation that classical scrapie is efficiently transmitted through contact with the placenta shed by infected ewes and that susceptibility is limited by polymorphisms in the prion protein gene, PRNP." (PMID 25888622, 2015). "We show that transgenic rabbits expressing a scrapie-susceptible ovine PRNP allele develop, at full attack rate, classical hallmarks of TSEs upon inoculation with scrapie prions, including fatal neurological diseases, clinical signs, PrPres deposition and vacuolation in the brain." (PMID 26248157, 2015). "In addition, susceptibility to scrapie in sheep is controlled by PRNP genotype at codons 136, 154 and 171; in Cheviot sheep ARR/ARR animals are resistant, VRQ homozygotes have the shortest incubation period and heterozygotes are intermediate." (PMID 25183238, 2014). "Our study shows that PRNP gene mutation K222 is strongly associated with resistance to classical scrapie also in experimental conditions, making it a potentially positive target for selection in the frame of breeding programs for resistance to classical scrapie in goats." (PMID 22296670, 2012). "Since sheep hosts of different PRNP genotypes differ in their level of susceptibility to isolates of scrapie, and scrapie eradication efforts are based on breeding genetics, a better understanding of the properties of the different strains will enhance options for control and eradication of scrapie." (PMID 22916207, 2012). "New insights in this new form of scrapie, that seems to be associated with PRNP codons 141 and 154, will probably have a major impact on the ongoing breeding programmes for reduced TSE susceptibility and will probably result in the development of adapted genotyping methods." (PMID 15769289, 2005). "In summary, scrapie is a complex disease that affects small domestic ruminants and is characterized by a peculiar etiological agent (more than 20 strains in classical scrapie and at least one demonstrated atypical one) that behaves differently if polymorphisms in the PRNP gene are present." (PMID 33806658, 2021). "Therefore, data about the distribution of the allele variants of PRNP in goats obtained from this investigation could contribute to direct breeding programs to reduce the possible risk of scrapie." (PMID 33525718, 2021). "However, the susceptibility of elk of different PRNP genotypes to scrapie isolates from sheep of different PRNP genotypes remains unknown." (PMID 30571737, 2018). "Differences in scrapie pathogenesis between mice and sheep may also reflect the influence of additional factors on disease in the natural host including other PRNP polymorphisms, and different involvements of the lymphoreticular system in sheep compared to Tg mice." (PMID 24204258, 2013). "In addition to those associated with scrapie, there are dozens more PRNP polymorphisms that may occur in various flocks." (PMID 20433741, 2010).
scrapie (continued). "Thus, eight PRNP codons and an octapeptide repeat have been associated with various forms of ovine prion disease, i.e. classical scrapie (codons 112, 136, 137, 154, 171, and 176), atypical scrapie (codon 141 and an octapeptide repeat insertion) and experimental BSE (codon 168)." (PMID 20433741, 2010). "The PRNP gene was identified as a key target of these studies because of its major role in scrapie resistance." (PMID 39806509, 2025). "The sheep PRNP genotype was VRQ/ARQ and therefore should be susceptible to scrapie via the oronasal route." (PMID 38394122, 2024). "The prion protein (PRNP) gene encoding prion protein is considered a prerequisite for the occurrence of scrapie disease, and knockout of the PRNP gene in transgenic goat is one effective approach to avoid scrapie." (PMID 35327291, 2022). "The transgenic mouse model Tg338 bearing the wild type ovine PRNP gene with VRQ polymorphisms, which easily propagates Nor98 isolates, was inoculated with both ShTgSPON and the atypical scrapie isolate." (PMID 36514160, 2022). "The staining in the cerebella is genotype-dependent at codon 171 of the PRNP gene in sheep with classical scrapie." (PMID 34960722, 2021). "This study adds information on genetic variability of the PRNP locus in goat populations/breeds, so contributing to the design of genetic control measure both in scrapie outbreaks and in disease prevention." (PMID 33525718, 2021). "Similar to scrapie in sheep, PRNP genotype can influence CWD pathogenesis in deer affecting PrPCWD deposition in peripheral tissues." (PMID 34488900, 2021). "The PRNP+/+ goats were euthanized at 615 dpi, when clinical signs of scrapie were observed in all four animals in the group." (PMID 31924264, 2020). "As demonstrated in sheep with scrapie, PRNP genotype strongly influences the tropism and distribution of PrP deposits." (PMID 30717795, 2019). "In sheep, the PRNP haplotypes VRQ, ARQ and ARR at codons 136, 154 and 171 play important roles in scrapie susceptibility." (PMID 31649311, 2019). "Recently, a strong genetic linkage between the PRNP gene and PRND gene was identified, and scrapie-associated SNPs were strictly linked to the genotype of the PRND gene." (PMID 30897750, 2019). "If so, it should be possible to make scrapie strain types visible in transgenic mice with various ovine (or caprine) PRNP expression levels." (PMID 31767033, 2019). "Results suggest there is adequate variation in the PRNP gene locus to support breeding programs for enhanced scrapie resistance in goats reared in Greece." (PMID 29879210, 2018). "Incubation period, disease progression, pathology and clinical presentation of classical scrapie in sheep are highly dependent on PRNP genotype, time and route of inoculation and prion strain." (PMID 30208891, 2018). "Polymorphic variation in the PRNP gene locus reported in our study enables the design and implementation of breeding programs towards enhanced scrapie resistance in goats reared in Greece." (PMID 29879210, 2018). "We also characterized the effect of polymorphisms occurring in elk PRNP sequence, 132L and 132M, when seeded with samples of the scrapie agent from sheep of these two PRNP genotypes." (PMID 30571737, 2018). "This further supports that scrapie samples from sheep of different PRNP genotypes can be distinguished by comparing seeding activities and biophysical properties of PrPSc after RT-QuIC using recombinant 132M elk prion protein." (PMID 30571737, 2018). "The results of the present study indicate that there is adequate variation in the PRNP gene locus to support breeding programs for enhanced scrapie resistance in goats reared in Greece." (PMID 29879210, 2018). "We also inoculated transgenic mice expressing 132M elk PRNP (Tg12) with the scrapie agent from different genotypes of sheep to compare with our RT-QuIC results." (PMID 30571737, 2018).
scrapie (continued). "In goats, among 39 genetic variations, PRNP codons 127, 142, 143, 146, 154, 211, and 222 are known to contribute to the resistance to scrapie." (PMID 30359416, 2018). "Classical scrapie is known to present with a variety of clinical signs, and clinical presentation is dependent on PRNP genotype, PrPSc strain, infective dose and age of host at infection." (PMID 30208891, 2018). "In contrast, the PrPRes associated with sheep Nor98 scrapie and human GSS linked to the P102L, F198S, A117V and H187R PRNP mutations include much smaller 6–14 kDa bands." (PMID 26086786, 2015). "The central role of PrPC in scrapie is illustrated by the fact that PRNP knockout mice are resistant to disease and by the reciprocal relationship between PRNP copy number and incubation period." (PMID 25183238, 2014). "Prions derived from brain tissue from sheep infected with classical scrapie of 8 different PRNP genotypes (at codons 136, 141 and 154) were used to seed PMCA reactions." (PMID 23153009, 2012). "Western blot analysis was performed on selected samples and showed that the molecular mass profiles remained unchanged following amplification of classical scrapie isolates of distinct PRNP genotypes in either ARQ or VRQ homozygous substrate." (PMID 23153009, 2012). "Atypical scrapie is also influenced by variations in PRNP and has been reported to occur in animals carrying genotypes conferring resistance to typical scrapie." (PMID 22044871, 2011). "For both scrapie cases S115/04 and S83, PRNP sequence analysis unanimously showed the homozygous PRNP genotype ARR/ARR." (PMID 17953092, 2007). "In order to minimize the risk of natural scrapie and presumed natural BSE in sheep, breeding programmes towards TSE resistance are conducted in many countries based on resistance rendering PRNP polymorphisms at codons 136 (A/V), 154 (R/H) and 171 (R/H/Q)." (PMID 15769289, 2005). "Known for over 250 years, scrapie is one of the TSE and encompasses zoonotic bovine spongiform encephalopathy (BSE) in cattle and Creutzfeldt–Jakob disease (CJD) in humans, which are regulated by the prion protein-encoding gene (PRNP)." (PMID 38355406, 2024). "It is well-known that the PRNP allele with amino acids: alanine (A), arginine (R), and arginine (R) at codons 136, 154 and 171, respectively (short: ARR), is most resistant to classical scrapie, whereas the VRQ allele is highly susceptible." (PMID 37888549, 2023). "There is no report on polymorphism of the PRNP gene in Nigerian sheep, despite its significant effects on scrapie, the economic importance of Nigerian sheep, and transmission of the diseases from animals to humans." (PMID 36892181, 2023). "The key residues of the ovine PRNP gene at codons 136, 154, and 171 have been reported as major determinants of susceptibility to scrapie, and the V136R154Q171 allele was considered the most susceptible factor to scrapie." (PMID 37808111, 2023). "The novel polymorphism at codon 118, which is found in the hydrophobic palindrome region, and at codon 127, which was located in the glycine-rich motif, may affect the conformational flexibility of PRNP and may introduce a novel form of scrapie in sheep." (PMID 37888549, 2023). "In addition, several studies have shown that variants at codons 142, 143, 146, 154, 171, 211, and 222 of the caprine PRNP gene affect scrapie progression in goats." (PMID 36204297, 2022). "The existence of genetic variation in resistance to various major endemic diseases in sheep has been highlighted, and one of the most well-known examples of marked assisted selection (MAS) is the case of the strong resistance to scrapie, conferred by specific genotypes at the prion gene (PRNP)." (PMID 35804527, 2022).
scrapie (continued). "The aim of this study was to identify PRNP genetic variability in goat breeds raised in the U.S. to assess its likely impact on scrapie occurrence in goats and evaluate the potential of implementing breeding management programs to enhance the prevalence of scrapie resistant variants." (PMID 34280230, 2021). "Additionally, further studies are needed to evaluate the protective level of PRNP genotypes in homozygous and heterozygous goats for an accurate assessment of breeding strategies to increase scrapie resistance in goats." (PMID 34280230, 2021). "Brain tissue homogenates from scrapie-free goats with wild type PRNP or polymorphisms (I142M, H143R, N146S, or Q222K) were deglycosylated prior to immunoblot for assessment of the relative abundance of the C1 fragment of PrPC." (PMID 34147084, 2021). "The complete open reading frame of PRNP was sequenced in all 12 goats to make sure that already-known polymorphisms associated with scrapie susceptibility would not bias the results." (PMID 31924264, 2020). "Since the SPRN gene is located on a different chromosome from the PRNP gene, previous association studies for scrapie susceptibility of the SPRN gene were clearly not the result of an LD block with the PRNP gene." (PMID 31649311, 2019). "However, the PRNP codon 143 SNP (with Arg instead of His) has been revealed to have a relatively weak influence on scrapie progression compared to two other SNPs at codon 146 (Asp or Ser, instead of Asn) and codon 222 (Lys instead of Gln)." (PMID 30359416, 2018). "In addition to in vitro assessment by RT-QuIC, we inoculated Tg12 mice (expressing 132M elk PRNP) with brain homogenates from sheep with clinical signs of scrapie." (PMID 30571737, 2018). "In this study, we utilized the in vitro assay, RT-QuIC, to evaluate how the PRNP genotype of the infectious seed influences the in vitro conversion using sheep scrapie agent of different genotypes and strains as a seed for RT-QuIC based conversion of 132M and 132L elk prion protein." (PMID 30571737, 2018). "The recent success in defining caprine PRNP gene variants that provide resistance to experimental and natural classical scrapie has prompted the authors to conduct a survey of PRNP genotypes in 10 goat breeds and 52 herds to find goats with the resistant K222 allele." (PMID 26755614, 2016). "Since our recipient sheep were euthanized at 25 mpi, the lack of preclinical scrapie in ARQ/VRQ recipient is very much unlikely due to the PRNP polymorphism at 136 codon." (PMID 26847623, 2016). "One factor known to contribute to scrapie transmission is PRNP genotype." (PMID 27393736, 2016). "It is possible therefore that some of these non-PRNP genes may, in some scrapie outbreaks, override the PRNP effects and result in either the appearance of disease in animals thought to be relatively resistant, or lack of disease in susceptible animals." (PMID 26587837, 2015). "In contrast to classical scrapie, the pathology in naturally-occurring cases of atypical scrapie appears more consistent, regardless of genotype, and is preserved on transmission within sheep homologous for the prion protein (PRNP) gene." (PMID 25710519, 2015). "With this CSSA assay, different ovine classical scrapie isolates with a range of PRNP genotypes could be differentiated from a similarly diverse set of atypical/Nor98 scrapie isolates." (PMID 26580664, 2015). "In addition, the use of AHQ/AHQ substrate did not support the amplification of any classical or atypical/Nor98 scrapie isolates from sheep with a range of PRNP genotypes." (PMID 26580664, 2015). "Here we report the results of a long term single study of experimental scrapie and BSE susceptibility of sheep of Cheviot, Poll Dorset and Suffolk breeds, originating from New Zealand and of a wide range of susceptible and resistant PRNP genotypes." (PMID 26587837, 2015).
scrapie (continued). "Even though goat scrapie prevalence is high in Greece, a clear association between specific caprine PRNP alleles and scrapie protection has not been determined, due to the lack of large-scale case-control studies." (PMID 24717012, 2014). "Nevertheless, a meta-analysis performed on the published data referring to PRNP genotypes from scrapie-affected Greek goats may lead to quite strong estimations." (PMID 24717012, 2014). "PRNP haplotypes valine/arginine/glutamine (VRQ) and alanine/arginine/glutamine (ARQ) at codons 136, 154, 171, respectively, are associated with high susceptibility to classical scrapie, whereas the ARR haplotype has been linked to resistance." (PMID 22296670, 2012). "Classical scrapie appears to consist of several strains which have most likely evolved gradually under the influence of different ovine PRNP genotypes and other yet unknown factors." (PMID 23116457, 2012). "PrPsc from 52 classical scrapie GB field isolates amplified in VRQ or ARQ or both substrates and supports the use of PMCA as a rapid assay for the detection of a wide range of ovine classical scrapie infections involving multiple PRNP genotypes and scrapie strains." (PMID 23153009, 2012). "In this study we sought to determine whether the PrPSc from scrapie infected sheep with diverse PRNP genotypes and from different locations in Great Britain could be amplified in vitro using the highly sensitive technique PMCA." (PMID 23153009, 2012). "In spite of the poorly defined effects of PRNP genetics, scrapie strain, dose, route and source of infection, the caprine placenta may represent a source of infection to progeny and herd mates as well as a source of persistent environmental contamination." (PMID 21284878, 2011). "In addition to the routine genotyping at codons 136–154 and 171, PRNP gene sequences from the 2 scrapie cases were determined by sequencing of PCR amplificates from brain-derived DNA to compensate for the possibility of a genetic chimerism in blood." (PMID 17953092, 2007). "Atypical scrapie has not been linked to a particular PRNP mutation, but the presence of phenylalanine in codon 141 and the presence of a histidine in codon 154 have been associated with this phenotype, however, these polymorphisms neither do account for all cases." (PMID 36514160, 2022). "Furthermore, more than 50 PRNP gene polymorphisms have been found, however, their role regarding the incubation period and the susceptibility to classical scrapie has not been adequately documented." (PMID 34438796, 2021). "Ovine PRNP haplotypes valine/arginine/glutamine (VRQ) and alanine/arginine/glutamine (ARQ) at codons 136, 154, 171 respectively, are associated with high susceptibility to scrapie, whereas the ARR haplotype has been linked to decreased susceptibility or even resistance." (PMID 29510738, 2018). "Using transgenic mice expressing ovine PRNP (ovinized mice), scrapie incubation times were substantially reduced compared with incubation times in wild-type mice while histopathologic profiles and PrPres biochemical features characteristic of scrapie prion types were maintained." (PMID 27393736, 2016). "However genes other than PRNP may also have a protective effect against scrapie and may have been selected in sheep breeds in NZ and Australia." (PMID 26587837, 2015). "Previous studies from this laboratory used the SSBP/1 sheep scrapie model in New Zealand sheep to describe the progression of pathology, as indicated by the detection of PrPSc, in different regions of the brain and peripheral lymphoid tissues, in sheep with defined PRNP genotypes." (PMID 25183238, 2014). "On this point, the polymorphic epitopes in goat PRNP gene might reveal a potential negative impact on the performances of diagnostic and discriminatory testing of goat scrapie where anti-PrP antibodies are used." (PMID 21961834, 2011).